NUP214 (nucleoporin 214)
Description:
Part of the nuclear pore complex. Has a critical role in nucleocytoplasmic transport. May serve as a docking site in the receptor-mediated import of substrates across the nuclear pore complex. (Microbial infection) Required for capsid disassembly of the human adenovirus 5 (HadV-5) leading to release of the viral genome to the nucleus (in vitro).
Synonyms: CAIN; CAN; D9S46E; N214; IIAE9
Tractability: Small molecule: a structure with a bound ligand is known; it has a high-quality binding pocket. PROTAC: UniProt records ubiquitination sites on it; ubiquitination databases record sites on it; its protein half-life has been measured.
Gene: Protein-coding gene on chromosome 9 (131,124,868 to 131,234,667, forward strand). Ensembl gene ENSG00000126883.
Subcellular location: Nucleus, nuclear pore complex
Pathways (Reactome):
Disease: Defective TPR may confer susceptibility towards thyroid papillary carcinoma (TPC); HCMV Early Events; HCMV Late Events; NEP/NS2 Interacts with the Cellular Export Machinery; NS1 Mediated Effects on Host Pathways; Nuclear import of Rev protein; Rev-mediated nuclear export of HIV RNA; SARS-CoV-2 activates/modulates innate and adaptive immune responses; Transport of Ribonucleoproteins into the Host Nucleus; Viral Messenger RNA Synthesis; Vpr-mediated nuclear import of PICs
Metabolism of RNA: HuR (ELAVL1) binds and stabilizes mRNA; Transport of Mature mRNA Derived from an Intronless Transcript; Transport of Mature mRNA derived from an Intron-Containing Transcript; Transport of the SLBP Dependant Mature mRNA; Transport of the SLBP independent Mature mRNA; snRNP Assembly; tRNA processing in the nucleus
Metabolism of proteins: SUMOylation of DNA damage response and repair proteins; SUMOylation of DNA replication proteins; SUMOylation of RNA binding proteins; SUMOylation of SUMOylation proteins; SUMOylation of chromatin organization proteins; SUMOylation of ubiquitinylation proteins
Metabolism: IP3 and IP4 transport between cytosol and nucleus; IP6 and IP7 transport between cytosol and nucleus; IPs transport between nucleus and cytosol; Regulation of Glucokinase by Glucokinase Regulatory Protein
Cell Cycle: Nuclear Pore Complex (NPC) Disassembly
Cellular responses to stimuli: Regulation of HSF1-mediated heat shock response
Immune System: ISG15 antiviral mechanism
Gene Ontology:
Molecular function: nuclear export signal receptor activity; protein binding; structural constituent of nuclear pore
Biological process: mRNA export from nucleus; protein export from nucleus; regulation of nucleocytoplasmic transport; nucleocytoplasmic transport; protein import into nucleus; RNA export from nucleus; intracellular protein transport
Cellular component: cytoplasmic side of nuclear pore; nuclear envelope; cytosol; nuclear pore; nucleoplasm
Genetic constraint (gnomAD): Loss-of-function variants: 63 observed, 169.91 expected, observed/expected ratio (o/e) 0.37, 90% interval 0.3 to 0.46. The upper end of that interval is the gene's LOEUF score, 0.46, which puts it in group 2 of 6, group 1 being the genes least tolerant of losing a copy. Missense variants: 2,360 observed, 2,522.2 expected, observed/expected ratio (o/e) 0.94, 90% interval 0.9 to 0.97. Synonymous variants: 990 observed, 997.28 expected, observed/expected ratio (o/e) 0.99, 90% interval 0.94 to 1.05.
Homologues: Orthologues: chimpanzee NUP214 (99% identical), macaque NUP214 (93% identical), dog NUP214 (85% identical), pig NUP214 (82% identical), rabbit NUP214 (80% identical), rat Nup214 (77% identical), mouse Nup214 (77% identical), Drosophila melanogaster Nup153 (8% identical). Paralogues in human: POM121 (14% identical), POM121C (12% identical), NUP153 (12% identical), POM121L2 (11% identical), NPAP1 (9% identical), POM121L12 (2% identical).
Diseases named in the same sentence as NUP214 in open-access papers:
NUP214 is named in the same sentence as 132 diseases in open-access papers, as found by Europe PMC text mining. Sharing a sentence is not in itself a finding about the gene and the disease. The quoted sentences say what the papers report.
leukemia (37 papers, 2009 to 2026). A malignant (clonal) hematologic disorder, involving hematopoietic stem cells and characterized by the presence of primitive or atypical myeloid or lymphoid cells in the bone marrow and the blood. "The remaining unremitted children included one with DEK::NUP214, one with secondary leukemia associated with KAT6A::CREBBP, and another with AXSL1 and SRSF2." (PMID 41264489, 2025). "Compared to other leukemia subtypes, NUP214-associated leukemia is highly aggressive and patients are frequently refractory to treatment, which coincides with overall poorer survival rates." (PMID 30669574, 2019). "So far, the precise pathogenic mechanism of Nup98- or Nup214-fusion–mediated leukemia still remains to be elucidated." (PMID 31755865, 2019). "The association of NUP214 fusion proteins with different leukemia subtypes suggests that distinct molecular mechanisms drive malignant transformation." (PMID 30669574, 2019). "Nucleoporin genes, Nup98 and Nup214, are often rearranged in leukemia and generate fusion genes that cause the development of the disease." (PMID 31755865, 2019). "Identifying NUP214 fusions is extremely important due to the diagnostic and therapeutic significance for leukemia patients." (PMID 25120641, 2014). "Nup88 was reported to interact with the FG repeat nucleoporin CAN/Nup214, another nucleoporin and a proto-oncogene implicated in leukemia during interphase." (PMID 20497554, 2010). "Nup88 interacts with the FG repeat nucleoporin CAN/Nup214, another nucleoporin and a proto-oncogene implicated in leukemia." (PMID 20497554, 2010). "However, the proportion of NOTCH1 mutation seems to be higher in SET-CAN/NUP214 positive leukemia patients." (PMID 37909026, 2023). "The scope of this review is to summarize the general features and prognostic significance in leukemia associated with the SET-CAN/NUP214 fusion gene and to discuss the methods of detection and treatment, aiming at providing some useful references for relevant researchers in the field of blood tumor." (PMID 37909026, 2023). "In addition, the existence of SET-CAN/NUP214 fusion gene is related to the up-regulation of the expression level of lymphoblastic leukemia-associated hematopoietic regulator 1(LYL1) and myocyte enhancer 2C(MEF2C) genes." (PMID 37909026, 2023). "Additionally, patients with NUP214 leukemia often present secondary mutations that influence the course of disease." (PMID 30669574, 2019). "Furthermore, it was shown that leukemia cells expressing Nup214-fusion are known to be associated with a high HOX gene expression profile." (PMID 31755865, 2019). "Among the multiple causes of leukemia, chromosomal translocations of the NUP214 gene may occur as a result of previous chemotherapy or as de novo genomic aberrations." (PMID 30669574, 2019). "The NUP214 fusions have significant diagnostic and therapeutic implications for leukemia patients." (PMID 25120641, 2014). "Overexpression of DEK::NUP214 induces proliferation of myeloid cells and leads to the development of leukemia in mice." (PMID 40204893, 2025). "In summary, XPO1 inhibition by eltanexor eradicated primary human DEK::NUP214 leukemia cells in vivo and proved an exceptional on-target sensitivity of these cells in a primary human AML model." (PMID 40148556, 2025). "Altogether, these results identified a novel function of DEK::NUP214 as an XPO1-dependent transcriptional activator of key leukemia drivers and provide a rationale to explore the use of XPO1 inhibitors in this patient population." (PMID 40204893, 2025). "Chromatin binding of XPO1 has also been shown in NPM1c and SET::NUP214 leukemia, suggesting that XPO1 mediates and stabilizes chromatin binding of DN." (PMID 40148556, 2025). "DEK was first identified as a fusion protein with nucleoporin 214 (NUP214), a component of the nuclear pore complex, in a leukemia-associated chromosomal translocation." (PMID 39984731, 2025).
leukemia (continued). "The first connection between a nucleoporin and a blood cancer, Nup214 in leukemia, was described almost 30 years ago." (PMID 38838144, 2024). "In summary, SET-CAN/NUP214 fusion gene is relatively rare in leukemia and mainly occurs in adult male T-ALL patients." (PMID 37909026, 2023). "CD7 was highly frequent in SET-CAN/NUP214 fusion gene positive leukemia, and the other immunophenotypes with higher frequency were cCD3, CD34, CD33 and CD13." (PMID 37909026, 2023). "Intriguingly, this upregulation of HOX genes is shared with NUP98::NSD1, DEK (DEK proto-oncogene)::NUP214 (nucleoporin 214), and NPM1 (nucleophosmin 1) mutated cases, suggesting HOXA and HOXB overexpression is a common alteration in leukemia development." (PMID 37325571, 2023). "The data revealed that although SET-CAN/NUP214 fusion gene occurs in various types of leukemia, it mainly occurs in T-ALL." (PMID 37909026, 2023). "In this review, we summarized the general features and clinical advances of SET-CAN/NUP214 fusion gene in leukemia." (PMID 37909026, 2023). "Fusion of ABL1 to BCR/TEL/NUP214 is observed in a large number of leukemia patients and allosteric stimulation of the normal ABL1 kinase activity enhanced the antileukemia effect of ABL1 tyrosine kinase inhibitors." (PMID 31537905, 2020). "A common feature of leukemias associated with these NUP98 and NUP214 fusions is the overexpression of HomeoboxA (HOXA) genes." (PMID 32343715, 2020). "The NUP98 and NUP214 nucleoporins (NUPs) are recurrently fused to heterologous proteins in leukemia." (PMID 32343715, 2020). "In the case of NUP214, four different fusion proteins have been reported in patients with leukemia: SET-NUP214, DEK-NUP214, SQSTM1-NUP214, and NUP214-ABL1." (PMID 32343715, 2020). "This notion is further supported by a recent study that showed successful disease remission for an AML patient with NUP214 driven leukemia who was treated with KPT-330 as single agent." (PMID 32934780, 2020). "We first determined the localization of NUP214 fusion proteins in different patient-derived leukemia cell lines with anti-NUP214 antibodies and immunofluorescence microscopy." (PMID 32934780, 2020). "Consistently, treatment of NUP214-rearranged leukemia cell lines with LMB or KPT-185 affects viability, metabolism, and proliferation, albeit to a different extent." (PMID 32934780, 2020). "The scope of this review is to summarize the general features of NUP214-related leukemia and discuss how distinct chromosomal translocation partners can influence the cellular effects of NUP214 fusion proteins in leukemia." (PMID 30669574, 2019). "The multiple functions of NUP214 fusion partners increase the complexity of potential roles of NUP214 fusion proteins in leukemia." (PMID 30669574, 2019). "Despite being a recurrent event, chromosomal translocations involving the NUP214 locus account for rare leukemia cases, which hampers the access of researchers to patients’ samples." (PMID 30669574, 2019). "It has been shown that some NUPs including NUP88, NUP98 and NUP214 make mechanistic contributions to carcinogenesis, particularly in leukemias." (PMID 29861858, 2018). "HOXA gene upregulation has previously been described in SET-NUP 214 leukemia, another NUP214-fusion gene leukemia, through binding to HOXA promoters." (PMID 26436590, 2015). "Mice inoculated with PML/RARα- or DEK/NUP214-positive leukemic cells developed leukemia with a latency of approximately 4 weeks and a penetrance of 100%." (PMID 25568664, 2014). "The cells originating from the PML/RARα-, RUNX1/RUNX1T1- or DEK/NUP214-positive LT-HSCs induced leukemia with a high penetrance of 70%, 50% or 80%, respectively." (PMID 25568664, 2014). "We found that the L-IC of PML/RARα-positive leukemia is different from the L-MC, as already described for DEK/NUP214-positive leukemia." (PMID 25568664, 2014).
leukemia (continued). "To further explore the response of DEK/NUP214-positive leukemia to ATO we exposed mice inoculated with DEK/NUP214-positive leukemic cells to ATO for 14 days starting at day 5 after inoculation." (PMID 25568664, 2014). "The mutations of NOTCH1, PHF6 and JAK1 are closely linked in the process of leukemia, which may be the secondary genetic alterations of SET-CAN/NUP214 fusion gene." (PMID 37909026, 2023). "Further research is needed to evaluate the role of SET-CAN/NUP214 fusion gene in leukemia." (PMID 37909026, 2023). "Taken together, our results suggest that CRM1 inhibition might be an interesting therapeutic option in NUP214-related leukemia, similarly as described for several cancer models, including other forms of leukemia." (PMID 32934780, 2020). "NUP98- and NUP214-related leukemia are associated with poor overall survival, and no specific or targeted therapies are as yet available to improve prognosis." (PMID 32664447, 2020). "Next, we questioned whether CRM1 inhibition by LMB and KPT-185 affects the survival of leukemia cell lines harboring NUP214 rearrangements." (PMID 32934780, 2020). "Our results indicate CRM1 as a possible therapeutic target in NUP214-related leukemia." (PMID 32934780, 2020). "Our findings may be of particular relevance in the search for new druggable targets, such as the MAPK and ER pathways, that might be explored in the development of specific therapies for NUP98 and NUP214 leukemia." (PMID 32664447, 2020). "e. how persistent are the effects of the two CRM1 inhibitors in NUP214-rearranged leukemia cells." (PMID 32934780, 2020). "Considering that NUP214 leukemia targets early hematopoietic progenitors, aberrant hypoacetylation mediated by the fusion proteins could lead to the silencing of genes important for lineage commitment and hematopoietic differentiation." (PMID 30669574, 2019). "However, one of the common features of both Nup98 and Nup214-fusion–expressing leukemia is aberrant activation of HOX genes." (PMID 31755865, 2019). "Recently, we showed that DEK/NUP214 initiates leukemia from LT-HSCs." (PMID 25568664, 2014). "We investigated whether activated STATs may mediate response to ATO treatment not only in PML/RARα but also in DEK/NUP214-positive leukemia." (PMID 25568664, 2014). "In summary, these data show that the AAFPs PML/RARα and DEK/NUP214 initiate leukemia by transforming a small subpopulation of LT-HSCs, but both maintain already established leukemia from already committed cell populations in the BM suggesting a difference between L-ICs and L-MCs." (PMID 25568664, 2014). "SET-CAN/NUP214 fusion gene may contribute to leukemia through direct and indirect effects." (PMID 37909026, 2023). "However, the precise mechanism by which DEK::NUP214 drives leukemia remains unclear." (PMID 40204893, 2025). "To validate the effect of eltanexor on DEK::NUP214 leukemia in vivo, we developed a serially transplantable PDX model of DEK::NUP214 AML." (PMID 40148556, 2025). "A DEK::NUP214 fusion was identified in five leukemias (cases 1-5), whereas SET::NUP214 and NUP214::ABL1 were found in two cases each (cases 6 and 7, and 8 and 9, respectively)." (PMID 38571499, 2024). "Most of these are recurrent and class-defining in pAML (for example, KMT2Ar, 20.3%; RUNX1::RUNX1T1, 12.4%), whereas we also found fusions recurrent in other leukemias, such as SET::NUP214 (n = 1) or SFPQ::ZFP36L2 (n = 1)." (PMID 38212634, 2024). "Chromosome abnormality involving NUP214 occur repeatedly in leukemia, in addition to the SET-CAN/NUP214 reviewed here, other chromosome abnormalities were found such as DEK-NUP214, SQSTM1-NUP214 and NUP214-ABL1." (PMID 37909026, 2023). "In general, the SET-CAN/NUP214 fusion gene is very rare in adult acute leukemia, more frequently found in T-ALL than in other types of leukemia, and more often in males." (PMID 35905214, 2022).
leukemia (continued). "Here we used patient-derived leukemia cell lines expressing endogenous SET-NUP214 and DEK-NUP214 to address the anti-cancer potential of CRM1 inhibition in NUP214-rearranged leukemia." (PMID 32934780, 2020). "DEK/NUP214 and PML/RARα exert their leukemogenic potential on a very small subpopulation of HSC explaining the low penetrance of leukemia from PML/RARα- and DEK/NUP214-transduced HSPCs." (PMID 25568664, 2014). "Of 141 human leukemia/lymphoma cell lines tested, only the T-ALL cell line LOUCY and the AML cell line MEGAL expressed the SET(TAF-Iβ)-NUP214 fusion gene transcript." (PMID 19166587, 2009). "Asciminib, an allosteric inhibitor used to treat BCR::ABL1+ leukemias, has demonstrated in vitro and in vivo efficacy for NUP214::ABL1 ALL as long as the ABL1 SH3 domain is present, supporting use of asciminib in NUP214::ABL1 ALL." (PMID 40247105, 2025). "Finally, the detection of both NUP214::ABL1 and PCM1::FGFR1 fusions in the near ETP-ALL of case 8 leaves no information as to which fusion was the primary and which was secondary in this leukemia." (PMID 38571499, 2024). "SET-CAN/NUP214 fusion gene is rare in leukemia patients, and there is no prospective clinical study for such patients." (PMID 37909026, 2023). "While BMP-like leukemias harbored fusion products known to drive high HOXA cluster expression, including MLLT10, KMT2A, NUP214, and direct HOXA::TCR fusions, T-specified leukemias had fusions to ZFP36L2 (involved in cell cycle control during T-cell beta selection) and TLX1/3." (PMID 37961674, 2023). "Our data suggest that CRM1 constraint is an interesting candidate for the development of an anti-cancer therapeutic approach in NUP214-related leukemia, for which no efficient targeted therapy has been developed so far." (PMID 32934780, 2020). "This is especially important, since no specific or targeted treatment options for NUP214 driven leukemia are available yet." (PMID 32934780, 2020). "Despite the functional proximity between NUP214 and CRM1-mediated nuclear export and the functional relevance of CRM1 in some leukemia, the impact of CRM1 inhibition in the context of NUP214-related leukemia has not been studied yet." (PMID 32934780, 2020). "The “leukemia maintaining” cell population of an already established DEK/NUP214-positive leukemia is not restricted to the original L-IC population." (PMID 25568664, 2014). "DEK/NUP214 and RUNX1/RUNX1T1 both induced leukemia with a low efficiency and long latency." (PMID 25568664, 2014). "We first validated the expression of the DEK::NUP214 and XPO1 genes and proteins in the FKH-1 cell line, using established leukemia cell lines as the negative control." (PMID 40148556, 2025). "SET-CAN/NUP214 fusion gene impairs the process of hematopoietic differentiation, but it alone is not sufficient to induce leukemia." (PMID 37909026, 2023). "In cells with a LT-HSC phenotype DEK/NUP214 only slows proliferation but does not block differentiation to a detectable level, and the viable cells harvested after the first plating still maintain stem cell capacity and thus are able to give rise to CFU-S12 and to induce leukemia." (PMID 25568664, 2014).